EGFR (epidermal growth factor receptor)
Diseases named in the same sentence as EGFR in open-access papers (continued):
Sharing a sentence is not in itself a finding about the gene and the disease.
lung adenocarcinoma (continued). "In lung adenocarcinoma patients experiencing disease progression to EGFR-TKI, histological transformation into small-cell lung cancer (SCLC), squamous-cell carcinoma (SqCC), and sarcomatoid carcinoma are known." (PMID 35888627, 2022). "Silencing SPP1 was found to reduce EGFR resistance to tyrosine kinase inhibitors and reduce its invasiveness in lung adenocarcinoma." (PMID 36138770, 2022). "We apply this “evolutionary triage” principle to TCGA data from EGFR-mutant, KRAS-mutant, and NEK (non-EGFR/KRAS) lung adenocarcinomas." (PMID 36612014, 2022). "EGFR, KRAS, and STK11 genes are known to be mutated in lung adenocarcinoma with a high frequency as well as ERBB2 with a lower frequency." (PMID 36499466, 2022). "In lung adenocarcinoma, activating mutations in oncogenes KRAS (32%), EGFR (11%), and BRAF (7%) are common." (PMID 36591457, 2022). "Four cases were reported that BRAF fusion was a mechanism of EGFR-TKI acquired resistance in EGFR mutant lung adenocarcinoma." (PMID 35912223, 2022). "In our study, the GAS5 SNP rs145204276 Ins/Del + Del/Del contributed to worse tumor condition concerning the tumor stage, tumor T status and lymph node status in lung adenocarcinoma patients with EGFR wild type." (PMID 36011604, 2022). "While common driver mutations in lung adenocarcinoma associated with low-TMB, usually female patients get higher EGFR mutations rate probability to have lower TMB that lead females not respond well to immunotherapy." (PMID 35479081, 2022). "In case 2, the EGFR ex20 P772_H773insYNP mutant lung adenocarcinoma patient with pleural metastasis had disease control using furmonertinib, a third-generation EGFR inhibitor." (PMID 36167530, 2022). "A male patient with stage IV lung adenocarcinoma who had NGS-detected MET amplification CN of 12 was treated with EGFR-TKI combined with crizotinib and achieved PR lasting for 14 months." (PMID 34953403, 2022). "A total of 250 patients with advanced lung adenocarcinoma (stage IIIc, n = 2; stage IVa, n = 92; stage IVb, n = 156) after progression on first- or second-generation EGFR TKIs were enrolled in our study." (PMID 35875167, 2022). "In this study, we aimed to determine the possible predictive or prognostic value of TMB in patients with EGFR-mutant lung adenocarcinoma that were treated with first-line TKIs." (PMID 36140210, 2022). "Radiomics markers that can predict the efficacy of first-line EGFR-TKI therapy are now more needed; we also have found two CT features for progression risk stratification to first-line EGFR-TKI remedy in advanced lung adenocarcinoma." (PMID 36052262, 2022). "Although EGFR-mutant lung adenocarcinoma patients with early onset LM reserve the opportunity to control their LM through targeted therapy, our results suggest that early onset LM independently predicts a poor outcome." (PMID 35740489, 2022). "EGFR is amplified and highly overexpressed in HNSCC and lung squamous cell carcinoma, frequently mutated and activated in lung adenocarcinoma (LUAC), and mutated, rearranged, and amplified in glioblastoma." (PMID 36294681, 2022). "In lung adenocarcinoma, carcinoembryonic antigen-related cell adhesion molecules can be considered as surrogate markers for epidermal growth factor receptor (EGFR) inhibitor sensitivity." (PMID 36357869, 2022). "Among the 185 pGGN lung adenocarcinomas, 122 (65.9%) were EGFR-mutant and 63 (34.1%) were EGFR-wild type." (PMID 36119545, 2022). "Gefitinib is a first-generation EGFR-TKI, which has good efficacy and tolerance for lung adenocarcinoma patients with EGFR-sensitive mutations and has been included in the Chinese medical insurance directory." (PMID 36230634, 2022). "This study will further explore the correlation between EGFR, ALK gene mutations and imaging and pathological features in invasive lung adenocarcinoma." (PMID 35340157, 2022).
lung adenocarcinoma (continued). "Next, we analyzed the clinical effects of the combination of HPV 16E6/18 E6 expression and EGFR expressions in 173 lung adenocarcinoma patients." (PMID 36358752, 2022). "Nevertheless, treatment options for LMC due to metastatic epidermal growth factor receptor-mutant (EGFR-mutant) lung adenocarcinoma are expanding." (PMID 35733652, 2022). "EMT is a hallmark of acquired resistance to EGFR-TKI and is associated with increased migration and invasion capacity of lung adenocarcinoma cells." (PMID 36362025, 2022). "The GSE32989 data provides the baseline gene expression profiles of 31 lung adenocarcinoma cell lines as well as their sensitivity (IC50) to two EGFR inhibitors (erlotinib and gefitinib)." (PMID 35016696, 2022). "Materials and Methods: This was a retrospective study conducted at Taichung Veterans General Hospital on patients with advanced EGFR-mutant lung adenocarcinoma receiving the third-generation EGFR-TKI." (PMID 35888627, 2022). "Patients with EGFR- or ALK-positive lung-adenocarcinoma showed a trend of better OS compared to those with other histopathologies (MST: 37.2 months vs. 14.6 months, p = 0.077) (Table A2)." (PMID 36199814, 2022). "EGFR mutation, one of the most common genetic events in NSCLC, accounts for 17%–61% of lung adenocarcinoma cases reported in a series of studies, with most frequently detected in Asian, female, non-smoking patients." (PMID 35571073, 2022). "In conclusion, this study confirmed that the 3rd generation EGFR-TKI osimertinib has a strong tumor suppressive effect on lung adenocarcinoma transplanted tumor through cell experiment and animal experiment of transplanted tumor." (PMID 35783156, 2022). "In EGFR-mutant lung adenocarcinoma, after treatment with tyrosine kinase inhibitors (TKIs), the majority of patients acquired subclonal drug-resistant mutations, such as MET, PD-L1, KRAS amplification, ESR1-AKAP12, and MKRN1-BRAF fusions." (PMID 35541919, 2022). "However, two other studies also successfully built a combined radiomic-clinical prediction model but also found that a deep learning feature-based model could also predict EGFR gene mutation status in patients with lung adenocarcinoma in a more accurate manner, achieving AUCs of 0.810 and 0.758." (PMID 35186727, 2022). "Multivariable analysis using Cox proportional hazard model and propensity score-matched analysis revealed that the combination of EGFR mutation and the presence of high-grade patterns was associated with poor RFS in resected stage I lung adenocarcinoma." (PMID 35266536, 2022). "Association between gene expression and immune infiltration levels in EGFR and diverse muscarinic receptor types were observed in lung adenocarcinoma and lung squamous cell carcinoma among several types of cancer." (PMID 35565451, 2022). "The histone deacetylase inhibitor vorinostat promotes ferroptosis in EGFR-mutant lung adenocarcinoma cells by inhibiting SLC7A11 (xCT) and enhancing the efficacy of ferroptosis inducers." (PMID 36712673, 2022). "Long-term survival differed according to nodal status by EBUS TBNA in recurrent lung adenocarcinoma, highlighting the importance of the use of EBUS TBNA, particularly for the differentiation of wild-type and mutated EGFR." (PMID 36292235, 2022). "We employed magnetic-activated cell sorting to isolate CAFs from a tumor surgically resected from a patient diagnosed with lung adenocarcinoma (mutant EGFR; low PD-L1)." (PMID 35884546, 2022). "Previous reports showed that afatinib as a first-line treatment provided better survival outcomes for advanced EGFR-mutant lung adenocarcinoma than gefitinib and erlotinib." (PMID 35806042, 2022). "BIBW-2992 was reported to inhibit the kinase activity of EGFR mutants and suppress lung adenocarcinoma development." (PMID 36171876, 2022).
lung adenocarcinoma (continued). "This study aims to construct a tumor microenvironment-based crosstalk between immunotherapy and epidermal growth factor receptor tyrosine kinase inhibitor (EGFR-TKI) in lung adenocarcinoma." (PMID 35154456, 2022). "We identified 193 patients with lung adenocarcinoma and brain metastasis treated with an EGFR TKI as their first-line systemic treatment." (PMID 36612183, 2022). "Patients with EGFR-driven lung adenocarcinoma experienced limited sites of progression while on therapy with an effective EGFR inhibitor." (PMID 35159026, 2022). "Thirty-nine EGFR ex20ins patients with stage IV lung adenocarcinoma started chemotherapy as first-line treatment, 15 patients received EGFR-TKI therapy as first-line therapy, and immunotherapy was administered as a first-line setting in 10 patients." (PMID 36119499, 2022). "First- and second-generation EGFR-tyrosine-kinase inhibitors (TKIs) revolutionized the treatment paradigm of advanced lung adenocarcinoma (LUAD)." (PMID 35156036, 2022). "They include five EGFR-mutant lung adenocarcinoma cell lines and one immortalized lung epithelial cell line AALE." (PMID 35840668, 2022). "EGFR mutation and ALK rearrangement are meaningful targetable driver alterations in lung adenocarcinoma (LUAD) and non-small-cell lung cancer (NSCLC), respectively." (PMID 35596192, 2022). "In this report, a 63-year-old woman with lung adenocarcinoma (LADC), harboring EGFR exon 18 G719D and exon 21 L861Q mutations, received first-generation, EGFR-tyrosine kinase inhibitor (TKI) icotinib therapy." (PMID 35957915, 2022). "Associations of SNPs of inflammation genes with PFS and OS of advanced lung adenocarcinoma patients treated with EGFR-TKIs." (PMID 35372081, 2022). "Limited studies have focused on an EGFR-TKI resistance-related gene signature (ERS) in lung adenocarcinoma (LUAD)." (PMID 36530971, 2022). "We have also highlighted the feasibility of non-invasively detecting the EGFR genetic status in lung adenocarcinomas using a machine learning model based on combined CT radiomic features and clinical characteristics." (PMID 36230590, 2022). "EGFR tyrosine kinase inhibitors (TKIs), as the first-line treatment for patients with EGFR-mutant lung adenocarcinoma, can significantly improve the prognosis and quality of life in this population." (PMID 35241046, 2022). "Common driver mutations (EGFR, ALK, BRAF, ERBB2, KRAS, MET, RET, and ROS1) analysis were performed in lung adenocarcinoma tissue samples from two PEAC patients (P08 and P10) using next-generation sequencing." (PMID 35172862, 2022). "The third-generation EGFR-TKI is one standard-of-care therapy for patients with EGFR-mutant lung adenocarcinoma." (PMID 35888627, 2022). "EGFR gene amplification and overexpression are frequent in several cancer types, including lung adenocarcinomas, colon carcinomas, and pancreatic adenocarcinomas." (PMID 36438567, 2022). "CAY10603, an inhibitor of HDAC6, acted synergistically with gefitinib to induce the apoptosis of lung adenocarcinoma cell lines by destabilizing EGFR, whereas sorafenib activated EGFR signaling by stabilizing HDAC6." (PMID 36076996, 2022). "In the present study, we demonstrated that patients with mutant lung adenocarcinoma with high D-dimer levels in their peripheral blood were less responsive to EGFR TKI, were more vulnerable to develop early disease progression, and had shorter survival." (PMID 35756605, 2022).
lung adenocarcinoma (continued). "Nowadays, the individual diagnosis and treatment of EGFR-mutant lung adenocarcinoma depend on invasive biopsy testing." (PMID 36052262, 2022). "Among the 185 GGO lung adenocarcinomas, 122 (65.9%) were EGFR-mutant and 63 (34.1%) were EGFR-wild type." (PMID 36119545, 2022). "Some of the commonly identified mutations associated with targeted therapies include, e.g., mutations in BRAF in cutaneous melanoma; KRAS, BRAF, and NRAS in colorectal cancer; and EGFR mutations and ALK and ROS1 gene rearrangements in lung adenocarcinomas." (PMID 35627184, 2022). "Therapeutic opportunities for EGFR mutant lung adenocarcinoma patients have radically changed because of the application of EGFR-TKI therapy." (PMID 36052262, 2022). "Identification of potential novel targets for reversing resistance to Epidermal Growth Factor Receptor (EGFR)-tyrosine kinase inhibitors (EGFR-TKIs) holds great promise for the treatment of relapsed lung adenocarcinoma (LUAD)." (PMID 35144642, 2022). "The presence of cancer stem cells became relevant due to the approximate 20% of advanced therapy-resistant PCa adenocarcinomas, and the 5% of EGFR mutant lung adenocarcinoma trans-differentiating to a neuroendocrine (NE) phenotype." (PMID 36135315, 2022). "According to the histological subtypes of NSCLC, lung adenocarcinoma (LUAD) and lung squamous carcinoma (LUSC) are associated with different mutational patterns, but are both mainly enriched for KRAS, EGFR, and ALK mutations." (PMID 36508072, 2022). "PTMs particularly phosphorylation of EGFR in lung adenocarcinoma, and SF3B1 in CLL has been reported/targeted." (PMID 35230971, 2022). "Through a regular follow-up, it was found that the tumor volume of EGFR-mutant lung adenocarcinoma decreased significantly during the application of targeted drugs for 2–3 months and then tended to become stable." (PMID 36153486, 2022). "To model the clinical exposure of EGFR TKIs in lung adenocarcinoma, we performed long-term treatments of osimertinib in these cell lines at a clinically relevant dose (100 nM) with periodic medium/TKI refreshment." (PMID 35867821, 2022). "EGFR-TKI-sensitive (PC9-6M) lung adenocarcinoma cells were treated with 0.1 μM concentration of Gefitinib or Erlotinib alone compared or in combination with TKIs- with increasing concentration of BR2-2xPPD peptides (0–2.5 μM) for 72 h." (PMID 35235599, 2022). "In univariate analyses, none of the factors, including the histopathological factors (EGFR/ALK-positive lung-adenocarcinoma vs. others), exhibited statistical significance, with the exception of extracranial metastatic status." (PMID 36199814, 2022). "Because of the frequent loss of TJ in transformation of epithelial tissues, we interbred DUSP3-knockout mice with EGFR-Del transgenic (Tg) mice and examined the effect of DUSP3 deficiency in lung adenocarcinoma (LAC) progression." (PMID 35705979, 2022). "Takada’s study retrospectively examined the relationship between PD-L1 expression and EGFR status in 441 surgically resected primary lung adenocarcinomas." (PMID 36159795, 2022). "For example, EGFR-TKI treatment suppresses glycolysis in parental EGFR-mutant lung adenocarcinoma lines and induces a dependence on mitochondrial oxidative phosphorylation (OxPhos) for cell survival." (PMID 35681591, 2022). "For EGFR-wild type pGGN lung adenocarcinomas, a small portion of the tumor and its proximal bronchovascular bundle were activated." (PMID 36119545, 2022). "Among lung adenocarcinoma patients with EGFR-mutant, ATG5 rs510432 have been proved to contribute to disease prognosis." (PMID 34661876, 2022). "All 9 patients with EGFR- or ALK-positive lung adenocarcinomas received a treatment with tyrosine kinase inhibitors (TKIs) before and/or after brain radiation therapy." (PMID 36199814, 2022). "Epidermal growth factor receptor (EGFR) tyrosine kinase inhibitor (TKI)-refractory lung adenocarcinoma (LUAD) progression is a major clinical problem." (PMID 34675407, 2022).
lung adenocarcinoma (continued). "During the past decade, the advancement of EGFR tyrosine kinase inhibitors (EGFR-TKIs) has revolutionarily transformed the landscape of treatment and prognosis of advanced lung adenocarcinoma patients." (PMID 35069906, 2022). "In lung adenocarcinomas patients, EGFR mediates the activation of RET with neuroendocrine differentiation characterized by ASCL1 expression, implicating that EGFR is a key regulator of RET." (PMID 36147490, 2022). "Data from 111 patients with EGFR-mutant lung adenocarcinoma who received thoracic radiotherapy were included in this retrospective study." (PMID 36153486, 2022). "The studied model, referred to as the in silico EGFR+ (Epidermal Growth Factor Receptor) Lung Adenocarcinoma (ISELA) model, relies on a mechanistic representation of tumor evolution, from specific mutations to tumor size evolution." (PMID 35796890, 2022). "Another previous study also reported that EGFR-MT lung adenocarcinomas have relatively lower 18F-FDG uptake in comparison with EGFR-WT tumors, and SUVmax of patients EGFR-21-MT was higher than that of EGFR-19-MT." (PMID 35800046, 2022). "Background and Objectives: Third-generation epidermal growth factor receptor (EGFR)-tyrosine kinase inhibitor (TKI) is one of the standard-of-care therapies in patients with EGFR-mutant lung adenocarcinoma; however, acquired resistance inevitably developed." (PMID 35888627, 2022). "This combined treatment also decreased the AXL levels and gefitinib resistance in EGFR-mutant HCC827 lung adenocarcinoma cells, thereby increasing apoptosis, suppressing the EMT, and eliminating cancer-cell stemness." (PMID 36547898, 2022). "Here, we report a female patient with advanced lung adenocarcinoma (LUAD), carrying a rare mutation of EGFR Exon19 E746_L747delinsIP, who was administered first-generation EGFR-TKIs as the first-line treatment." (PMID 35712479, 2022). "Fortunately, the testing of epidermal growth factor receptor (EGFR) alterations serves as a targeted therapy recommendation to guide treatment selection in patients with lung adenocarcinoma." (PMID 35053473, 2022). "Next-generation sequencing was performed to analyze epidermal growth factor receptor (EGFR) and BRAF mutational status in all cases of lung adenocarcinoma." (PMID 36422072, 2022). "The tight correlation between radiotherapy and immune status has been confirmed and the prognostic value of SII in patients with BMs from EGFR-mutant lung adenocarcinoma who underwent brain radiotherapy remains elusive." (PMID 35241046, 2022). "In previous studies, most of the genes with germline mutations in lung adenocarcinoma were typical oncogenes and proto-oncogenes, which included BRCA2, CHECK2, CDKN2, BAP1, EGFR." (PMID 35712480, 2022). "The data demonstrated that EGFR-TKIs are effective and well-tolerated in lung adenocarcinoma patients with poor PS." (PMID 35158940, 2022). "EGFR-TKIs have been shown to exert their action by inhibiting the phosphorylation of Hsp70 and stimulating its ubiquitination in lung adenocarcinoma cells resulting in this protein’s degradation." (PMID 36558926, 2022). "Epidermal growth factor receptor-tyrosine kinase inhibitors (EGFR-TKIs) showed potency as a non-invasive therapeutic approach in pure ground-glass opacity nodule (pGGN) lung adenocarcinoma." (PMID 36119545, 2022). "The reasons for the discordance cannot be fully elucidated and further studies are needed to validate the ITH in EGFR-mutant lung adenocarcinoma." (PMID 35847947, 2022). "We have reported a rare case of lung adenocarcinoma with a novel EGFR–intergenic region (IGR) (SEC61G) fusion (the mutation frequency was 79.8%) and EGFR amplification (copy number: 5.6)." (PMID 35903676, 2022). "Compared to those with wild-type EGFR, AXL was overexpressed more frequently in lung adenocarcinomas harboring EGFR-activating mutations." (PMID 36482474, 2022).